MX1 (MX dynamin like GTPase 1)
Diseases named in the same sentence as MX1 in open-access papers (continued):
Sharing a sentence is not in itself a finding about the gene and the disease.
oral cancer (4 papers, 2020 to 2026). "We previously reported that environmental stresses of saliva-like hypotonicity and beverage-like temperature changes triggered cycles of disassembly/reassembly of biomolecular condensates of GFP-tagged human myxovirus resistance protein (MxA; alias Mx1) in oral cancer cells." (PMID 42274575, 2026). "However, in our study, we found that exposure to WPS smoke in oral epithelial cells induced expression of MX1, indicating its possible oncogenic role in oral cancer." (PMID 32961854, 2020).
parasite infection (4 papers, 2014 to 2022). "C57BL/6 mice infected with N67 parasite induced a strong IFN-I response, including increased expression of genes such as Cd40, Isg15, Isg20, Ifit2, Mx1, Mx2, Ddx58, and Usp18 genes, leading to suppression of N67 parasitemia." (PMID 27716849, 2016). "Using Mx1 transcript abundance as a read-out for host response to parasite infection, three strains of Neospora and four strains of Toxoplasma were tested for induction of the type I interferon program." (PMID 24505488, 2014). "Over both species, the strongest biomarkers for discrimination between viral and bacterial/parasitic disease were UBL1 (PXMP2), IFIT5, GAL3, NFX, VHSVIP4 (VIG4), DEXH (DDX58), unknown CA054694 MX1 RSAD, IFI44A, and HERC6." (PMID 28702195, 2017).
periodontitis (4 papers, 2022 to 2025). An acute or chronic inflammatory process that affects the tissues that surround and support the teeth. "These genes, OAS2, MX1, and MX2, have been linked to the response of immunological pathways in rheumatoid arthritis and periodontitis." (PMID 38323815, 2024). "They find that IF135, MX1, SPI1 and IF144L associated with it are in the periodontitis core PPI network, and C1QB in the periodontitis core ceRNA network." (PMID 38919957, 2024). "It is known that the gene expressions of MX1 and IFIT1 in peripheral blood neutrophils of individuals with periodontitis are upregulated." (PMID 39669221, 2025).
pneumonia (4 papers, 2021 to 2023). An acute, acute and chronic, or chronic inflammation focally or diffusely affecting the lung parenchyma, caused by an infection in one or both of the lungs (by bacteria, viruses, fungi, or mycoplasma.). "In pneumonia, the microRNA network controls the replication of human macrophages through LGALS8 and MX1." (PMID 34868310, 2021).
renal fibrosis (4 papers, 2023 to 2025). A final common manifestation of a wide variety of chronic kidney diseases characterized by glomerulosclerosis and tubulointerstitial fibrosis. "The in vivo and in vitro experiments indicated that the loss of KLF5 relieved renal fibrosis and injury in LN via downregulating the transcription level of MX1." (PMID 37506140, 2023). "In conclusion, our study elucidated the protective effect of the loss of KLF5 by inhibiting the transcription level of MX1 in LN‐induced renal fibrosis and injury." (PMID 37506140, 2023). "In our previous study, KLF5 was found to act as a suppressor in renal fibrosis through regulating MX1." (PMID 39412062, 2024). "Subsequent functional experiments revealed that the mRNA level of MX1 was increasingly expressed in renal tissues and downregulation of MX1 relieved renal fibrosis and injury in MRL/lpr mice." (PMID 37506140, 2023). "In addition, we also found that renal fibrosis was enhanced in Mx1;TβRICA-CKD mice, confirming that TβRI overexpression induced renal failure." (PMID 40141345, 2025). "Knockdown of KLF5 mitigated renal fibrosis in LN by inhibiting MX1 transcription." (PMID 37506140, 2023). "Knockdown of KLF5 alleviated renal fibrosis in LN through repressing the transcription of MX1." (PMID 37506140, 2023). "Hence, KLF5 regulated renal fibrosis and injury in LN via MX1." (PMID 37506140, 2023). "Injection of sh‐KLF5 or sh‐MX1 alone in MRL/lpr mice reduced renal fibrosis in LN, while simultaneous injection of sh‐KLF5 and ad‐MX1 exacerbated renal injury and fibrosis." (PMID 37506140, 2023). "However, the role of MX1 in renal fibrosis in LN remains largely unknown." (PMID 37506140, 2023). "To further explore the biological function of KLF5 and MX1 in the progression of renal fibrosis, we transfected si‐KLF5 or cotransfected si‐KLF5 and oe‐MX1 into HK‐2 cells, followed by 24‐h stimulation with TGF‐β1." (PMID 37506140, 2023).
Sjögren's Syndrome (4 papers, 2018 to 2025). "Low MX1 levels were shown to be associated with both a low disease activity score based on the European League Against Rheumatism (EULAR) Sjögren's Syndrome Disease Activity Index (ESSDAI) and hydroxychloroquine use in all patients." (PMID 31241661, 2019). "Additionally, genes related to type I-IFN activity including, ICSBP1, MX1, IFITM1, IFITM2, IRF9, were found to be overexpressed in patients with Sjogren’s syndrome." (PMID 36059459, 2022).
alopecia areata (3 papers, 2006 to 2023). Loss of scalp and body hair involving microscopically inflammatory patchy areas. "A previous genetic association study linked intronic polymorphisms in the MX1 gene to the inflammatory hair loss disorder alopecia areata." (PMID 16539728, 2006). "A link between MX1 and sporadic alopecia areata has been raised by a reasonably large genetic association study, including 165 alopecia areata cases and 510 controls, which showed that the +9959 intronic polymorphism conveyed a 1.79-fold increase in risk." (PMID 16539728, 2006). "It is worth mentioning that MX1, located on chr21, is a downstream effector-gene of I-IFN, and associated with Alopecia areata (AA) in DS." (PMID 38066591, 2023).
colon carcinoma (3 papers, 2019 to 2024). "In a study of primary colon cancer, genes such as IGBP3, OAS2, MX1, and Robo2 were found as prognostic markers in an independent series of colon cancer patients." (PMID 36759842, 2023). "The therapeutic benefits of cocoa consumption and colon cancer risk could be featured with regulatory modulations of ISG15, MX1, and STAT as the central tumor suppressor genes in the protein-protein interaction network." (PMID 30949322, 2019).
head and neck cancer (3 papers, 2021 to 2024). A primary or metastatic malignant neoplasm affecting the head and neck. "Epigenetic silencing of MX1 has been reported in head and neck cancer and this was re‐activated by the demethylating agent 5‐aza‐2′‐deoxycytidine." (PMID 39285636, 2024).
Immunodeficiency (3 papers, 2022 to 2025). Failure of the immune system to protect the body adequately from infection, due to the absence or insufficiency of some component process or substance. "The identification of MX1+ monocytes as a critical mediator highlights the potential of MSC therapy to modulate immune dysfunction in DLC." (PMID 40721581, 2025).
rheumatoid arthritis (3 papers, 2021 to 2024). A chronic, systemic autoimmune disorder characterized by inflammation in the synovial membranes and articular surfaces. "MX1 belongs to IFN-regulated genes, and its different methylation profile was also observed in patients with rheumatoid arthritis and Sjorgen’s syndrome, thus suggesting the potential role of MX1 methylation in inflammatory responses as well." (PMID 39199374, 2024).
tuberculosis (3 papers, 2018 to 2020). A chronic, recurrent infection caused by the bacterium Mycobacterium tuberculosis. "In the current study, six genes (IFITM1, IRF9, MX1, OAS1, STAT1, and STAT2) of the “host response signature network” are significantly overlapping with the “human immune response to tuberculosis” pathway with p-value 1.57e-8." (PMID 33362771, 2020).
type 1 diabetes (3 papers, 2021 to 2023). "We found that MX1 was upregulated in new-onset type 1 diabetes and that MX2 was upregulated in longstanding type 1 diabetes as well as having two eQTL SNPs." (PMID 33973017, 2021). "In conjunction, we found polymorphisms in OAS, MX1 and IFIH1 that indicate predisposition to type 1 diabetes." (PMID 33973017, 2021).
acute leukemia (2 papers, 2013 to 2021). A clonal (malignant) hematopoietic disorder with an acute onset, affecting the bone marrow and the peripheral blood. "Surprisingly, both the hematopoietic R26PR;Mx1-cre and mammary R26PR;MMTV-cre lines very rapidly developed and succumbed to acute leukemia." (PMID 24046360, 2013).
acute myeloid leukemia (2 papers, 2016). Acute myeloid leukemia (AML) is a group of neoplasms arising from precursor cells committed to the myeloid cell-line differentiation. "A conditional knockin line, in which Mll-AF4 was induced by Mx1-Cre in adult animals, developed both pre-B ALL and acute myeloid leukemia (AML) with a shorter latency that was still around 150 days." (PMID 27396339, 2016).
Aicardi-Goutières syndrome (2 papers, 2021). "We next examined baseline gene expression (qPCR) of archetypal interferon stimulated genes (ISGs) IFI27, USP18, MX1, OASL, IRF7, and MX2, and those ISGs found highly expressed in PBMCs from the type 1 interferonopathy, Aicardi-Goutières syndrome (AGS) patients (IFI27, ISG15, IFI44L, and RSAD2)." (PMID 33746960, 2021).
Arthritis (2 papers, 2019 to 2021). Inflammation of a joint. "There was not a statistically significant difference (p>0.05) between the serum levels of MX1 according to the presence of lymphadenopathy, parotid involvement, arthralgia/arthritis, skin involvement, pulmonary involvement, cryoglobulinemia, hypocomplementemia and neutropenia." (PMID 31241661, 2019).
Autoimmunity (2 papers, 2011 to 2017). The occurrence of an immune reaction against the organism's own cells or tissues. "We believe that anti-MX1 autoantibody have the potential to expand the definition of autoimmunity in IIPs." (PMID 28230086, 2017).
colitis (2 papers, 2017 to 2022). Inflammation of the colon. "Similarly, Mx1-Cre;Gankyrinf/f mice exhibited attenuated inflammatory scores upon acute DSS colitis model." (PMID 28160571, 2017).
dermatitis (2 papers, 2019 to 2023). An inflammatory process affecting the skin. "Among the generated regulatory network, STAT1, IFITM1, ISG15, and MX1 were genes associated with the IFN signaling pathway, while STAT1 and MX1 were associated with dermatitis, and STAT1 and ISG15 were associated with the inflammatory response." (PMID 30634634, 2019).
Ebola (2 papers, 2016 to 2024). "They found that bat MX1 proteins are key factors in controlling viral replication, including Ebola, in their bat hosts, and offer insights into the coevolution of these proteins with bat-borne viruses." (PMID 39282474, 2024). "By impacting the “viral life cycle” (GO:0019058) and actively participating in “cytokine-mediated signaling pathways” (GO:0019221), MX1 emerges as a pivotal factor in the immune system's strategy to combat Ebola." (PMID 39282474, 2024).
endothelial dysfunction (2 papers, 2025). In vascular diseases, endothelial dysfunction is a systemic pathological state of the endothelium (the inner lining of blood vessels) and can be broadly defined as an imbalance between vasodilating and vasoconstricting substances produced by (or acting on) the endothelium. "MX1 has antipathogenic and proinflammatory functions, which have been reported to be associated with the depletion of vascular endothelial progenitor cells and endothelial dysfunction." (PMID 40421421, 2025).
gastric cancer (2 papers, 2019). A primary or metastatic malignant neoplasm involving the stomach. "For all gastric cancer cases, our results showed that high ERBB2 expression was associated with the worse overall survival of GC patients, VIM, IFI44, IFIT2, and MX1 showed similar associations (P < 0.05)." (PMID 31949544, 2019).
head and neck squamous cell carcinoma (2 papers, 2015 to 2023). A squamous cell carcinoma that arises from any of the following anatomic sites: lip and oral cavity, nasal cavity, paranasal sinuses, pharynx, larynx, and salivary glands. "The Mx1 gene has been found to be hypermethylated and suppressed in primary head and neck squamous cell carcinoma cell lines and tissue samples compared with normal lymphocytes." (PMID 26411585, 2015).
inflammatory bowel disease (2 papers, 2021 to 2025). A spectrum of small and large bowel inflammatory diseases of unknown etiology. "Inflammatory bowel disease was inversely associated with GATE scores for 5 interferon-stimulated genes—IFIT1, IFI44, HERC5, MX1, IFI44L—regulated by the same trans-expression quantitative trait locus, and with the GATE score for IFNL1." (PMID 40996888, 2025).
Insulin resistance (2 papers, 2013 to 2025). Increased resistance towards insulin, that is, diminished effectiveness of insulin in reducing blood glucose levels. "We show through both Mx-1 Cre mice and CpG-Stat3 siRNA that blocking Stat3 in B and myeloid cells can effectively reduce insulin resistance." (PMID 40801626, 2025).
liver cancer (2 papers, 2023 to 2024). An epithelial or non-epithelial malignant neoplasm that arises from the liver. "The experimental data clarify a confusing issue and argue against application of the Mx1-Cre system to liver cancer research." (PMID 36828281, 2023). "Of note, the Mx1-cre system with polyIC induction still is being used in liver cancer research, but the results could be misleading because of the complicated antitumorigenic or protumorigenic effects of the synthetic double-stranded RNA (dsRNA) that induces a milieu of inflammatory cytokines." (PMID 36828281, 2023).
lung disease (2 papers, 2008 to 2021). "Oral apoAI mimetic peptides like 6 F (Tg6F) directly bind not only bioactive lipids but also microbial products like LPS to alter intestinal immune cells and the expression of genes including IFNβ1 and MX1 levels, leading to similar changes in lung and reduced lung disease such as cancer." (PMID 34494942, 2021).
myeloid malignancies (2 papers, 2016 to 2024). "Interestingly, we have not observed the development of myeloid malignancies in EμSRα-tTA;Teto-Cre;Dnmt3afl/fl;Rosa26LOXPEGFP/EGFP model, despite the fact that Dnmt3a – like in Mx1 - Cre;Dnmt3afl/fl model – is conditionally inactivated in HSPCs and all hematopoietic lineages." (PMID 27677595, 2016).
myeloproliferative neoplasm (2 papers, 2020 to 2022). A clonal hematopoietic stem cell disorder, characterized by proliferation in the bone marrow of one or more of the myeloid (i.e., granulocytic, erythroid, megakaryocytic, and mast cell) lineages. "When Mindbomb-1 (Mib1), an essential gene for Notch ligand endocytosis, was deleted (Mx1-cre; Mib1−/− mice or MMTV-cre, Mib1−/−1 mice), the mice developed de novo myeloproliferative neoplasm (MPN), which is attributable to the loss of Mib1 from the bone marrow microenvironment." (PMID 33585446, 2020).
neutropenia (2 papers, 2016 to 2019). A decrease in the number of neutrophils found in the blood. "Cebpa Enh(f/f);Mx1-Cre mice develop related changes, with neutropenia, reduced GMP, LSK expansion, and increased BFU-E." (PMID 26937964, 2016).
Osteopenia (2 papers, 2023 to 2025). Osteopenia is a term to define bone density that is not normal but also not as low as osteoporosis. "As expected, uCT and histomorphometry analyses found that the overexpression of TβRI in Mx1-TβRICA mice induced osteopenia." (PMID 40141345, 2025). "Microindentation testing revealed that Mx1;TβRICA mice had decreased bone hardness consistent with osteopenia from μCT and histomorphometric analysis." (PMID 37445982, 2023). "Mx1;TβRICA-CKD mice displayed severe osteopenia as assessed by uCT in both femurs and mandibles." (PMID 40141345, 2025).
osteosarcoma (2 papers, 2009 to 2023). A usually aggressive malignant bone-forming mesenchymal neoplasm, predominantly affecting adolescents and young adults. "Taken together, our data support a role of ISG15 and MX1 in canine osteosarcoma." (PMID 38201229, 2023). "While the role of ISG15 or MX1 in osteosarcoma is not well-studied, a recent study identified ISG15 as a potential therapeutic target in human OSA patients." (PMID 38201229, 2023).
Pancytopenia (2 papers, 2022 to 2025). An abnormal reduction in numbers of all blood cell types (red blood cells, white blood cells, and platelets). "After initial poly I:C injection for 12 days, the recipient mice reconstituted with Myh9fl/fl:Mx1-cre BM cells showed a drastic reduction of HSCs, HPCs, and other hematopoietic precursor cells in BM, along with a typical pancytopenia in peripheral blood and, finally led to death." (PMID 35740994, 2022).
pulmonary arterial hypertension (2 papers, 2022 to 2025). Pulmonary arterial hypertension (PAH) is a group of diseases characterized by mean pulmonary artery pressure >20 mmHg and elevated pulmonary arterial resistance leading to right heart failure. "Increased levels of interferon (IFN) regulated genes such as Siglec 1 and MX1 have been reported in monocytes isolated from lcSSc patients, especially lcSSc associated with pulmonary arterial hypertension." (PMID 35310606, 2022).
Salmonella Infections (2 papers, 2021 to 2022). Infections with bacteria of the genus SALMONELLA. "Although IFN-/ does not directly activate the MX1 gene, evidence demonstrates that it is involved in the host response to Salmonella infection." (PMID 34960172, 2021).
T-cell lymphomas (2 papers, 2013 to 2016). "In fact, T-cell lymphomas and lung adenomas have been described in KrasG12D mice with Cre expressed via adenovirus and Mx-1 respectively." (PMID 23825691, 2013).
uveitis (2 papers, 2024 to 2025). An inflammatory process affecting a part of or the entire uvea. "Several metaDEGs from the uveitis only group, including IFIT3, IFI44, IFITM1, MX1, TLR7 and DHRS9, and gene hubs from the modular co-expression analyses of the systemic disease-associated uveitis group are critical players in interferon-induced immune responses." (PMID 40270958, 2025).
vitiligo (2 papers, 2023 to 2024). Generalized well circumscribed patches of leukoderma that are generally distributed over symmetric body locations and is due to autoimmune destruction of melanocytes. "Leptin deficiency also resulted in significantly lower expressed vitiligo-related genes, such as Cxcl9 (p = 0.0497), Gzmb (p < 0.001), Ifng (p = 0.0159), and Mx1 (p < 0.001) after modeling." (PMID 37207234, 2023). "In mice, LEPTIN deficiency ameliorated the development of vitiligo and reduced the expression of Cxcl9, Gzmb, Ifng, and Mx1 in vitiligo lesions." (PMID 38421796, 2024). "RT-qPCR showed that the expression of vitiligo-related genes Mx1 in C57 BL/6 Lep KO mice was significantly lower than that in C57 BL/6 WT mice (p < 0.001)." (PMID 37207234, 2023).
allergic asthma (1 paper, 2022). A asthma with a basis in a pathological type I hypersensitivity reaction. "MX1, RSAD2, IFIT1, IFI27, OAS3, and SAMD9L were markedly elevated in HDM-treated mice and positively associated with IL-5, IL-13 and MUC5AC (key mediators of allergic asthma)." (PMID 36211429, 2022). "Furthermore, MX1, RSAD2, IFIT1, IFI27, OAS3, and SAMD9L levels correlated positively with IL-5, IL-13, and MUC5AC levels, which are the key mediators of allergic asthma." (PMID 36211429, 2022).
allergies (1 paper, 2014). "Hence, using house dust for diagnosis is similar to general screening of allergies with allergen mixes, such as fx1, fx5, mx1, and Phadiatop of UniCAP." (PMID 24778467, 2014).
alveolitis (1 paper, 2019). "The r19FCX4C virus effectively reversed this increase with primary r19F infection as indicated by interstitial inflammation and alveolitis and levels of MX1, TNF-α, INF-g, and MCP-1 mRNA in lung tissue." (PMID 31330970, 2019).
antisynthetase syndrome (1 paper, 2025). Antisynthetase (AS) syndrome is a clinically heterogeneous form of idiopathic inflammatory myopathy characterized by myositis, arthralgia, Raynaud phenomenon, mechanic hands, interstitial lung disease (ILD), and serum autoantibodies to aminoacyl transfer RNA synthetases (anti-ARS). "Type I IFN-inducible genes, such as ISG15 and MX1, were elevated at intermediate levels, lower than those seen in DM but similar to antisynthetase syndrome." (PMID 40568658, 2025).